MMP9 (matrix metallopeptidase 9)
Diseases named in the same sentence as MMP9 in open-access papers (continued):
Sharing a sentence is not in itself a finding about the gene and the disease.
diabetes (continued). "In patients with diabetes different MMPs such as MMP-2 and MMP-9 are increased in urine, especially in patients with albuminuria and established renal injury." (PMID 32046355, 2020). "In diabetes, lysine demethylase (LSD1) enhanced glucose-induced decrease in H3K9me2 and increase in p65 at the MMP-9 promoter, and this demethylation releases lysine 9 for acetylation." (PMID 32695308, 2020). "Additionally, in connection to other cardiac parameters, nobiletin reduced MMP-2 and MMP-9 enzymatic activities in the heart, improved the cardiac hypertrophy index, attenuated the deterioration in the morphology of cardiomyocytes, and reduced diabetes-induced myocardial fibrosis in the rats." (PMID 32977511, 2020). "According to these studies, diabetes duration has a significant role on the alteration of urinary MMP2 and MMP9." (PMID 30396876, 2019). "Investigate effects of long-term exercise on the remodeling markers MMP-9, TIMP-1, EMMPRIN and Galectin-3 in combined type 2 diabetes mellitus (T2DM) and coronary artery disease (CAD) patients." (PMID 31890043, 2019). "The oxidative stress parameters were significantly (Mann-Whitney test p < 0.002) increased after diabetes was induced, as well as glycemia, hepatic enzymes, and matrix metalloproteinases (MMP-2 and MMP-9)." (PMID 30818888, 2019). "We examined the serum MMP-2 and MMP-9 activity at 72 h after MCAO and found that the development of diabetes increased the serum levels of MMP-2 and MMP-9, which were further elevated after rt-PA treatment." (PMID 30953513, 2019). "Mmp-9 staining (P < 0.01) as well as FSP-1 (P < 0.01) was both abolished in TG-STZ mice, in comparison with their WT diabetes littermates at the indicated time points." (PMID 29497040, 2018). "Collectively, these data strongly suggested that long-term diabetes conditions upregulated MCP-1, MMP-9, NOX2, and NOX4 via ERK2/3 phosphorylation." (PMID 30308936, 2018). "Previous reports have shown that MMP-2 and MMP-9 activities were significantly upregulated in diabetic heart, and inhibition of MMP activities is considered to have a cardioprotective role in diabetes." (PMID 29760746, 2018). "Activation of Ezh2 in diabetes, via trimethylation of H3K27, facilitates recruitment of the enzymes responsible for regulation of DNA methylation of the MMP-9 promoter, resulting in its transcriptional activation." (PMID 29261844, 2017). "In our study, diabetes markedly increased TIMP-1 expression and reduced MMP-9/TIMP-1 ratio, leading to reduced MMP-9 gelatinase activity." (PMID 28894114, 2017). "This work identifies novel diabetes related differences in circulating and wound tissue neutrophil NGAL and MMP-9." (PMID 28182694, 2017). "Diabetes significantly increased implant neutrophil NGAL and MMP-9 protein as well as NGAL mRNA, wound fluid NGAL/MMP-9 complex and MMP-9 activity (all <0.05)." (PMID 28182694, 2017). "Contrary to MMP-9 and −13 upregulation, we detected downregulation of MMP-14 in diabetic kidney, which was ameliorated by GYY." (PMID 28883608, 2017). "In skin wound tissue compared with control, diabetes increased neutrophil infiltration, NGAL mRNA and MMP-9 protein (P<0.05)." (PMID 28182694, 2017). "Diabetes activates matrix metalloproteinase-9 (MMP-9), and MMP-9 via damaging retinal mitochondria, activates capillary cell apoptosis." (PMID 29261844, 2017). "The effect of diabetes on NGAL and MMP-9 was first examined in skin wound granulation tissue at day 6 post wounding." (PMID 28182694, 2017). "To examine in more detail the effect of diabetes on wound inflammatory cells and in particular neutrophil NGAL and MMP-9 we used a PVC implant model." (PMID 28182694, 2017). "Among them, MMP9 and CTGF are crucial in virtually all diabetes-induced fibrotic pathology, including nephritic, retinal, and cardiac fibrosis." (PMID 27519769, 2016).
diabetes (continued). "The MMP-9 concentrations in PRP treated patients, DM patients with diabetes ≥ 10 years and recurrent DME within 3months were elevated (p = 0.023, p = 0.011, and p = 0.027, respectively)." (PMID 27467659, 2016). "Endothelin-1 (ET-1) and matrix metallopeptidase-9 (MMP-9) have been implicatedin the development of cardiovascular diseases, diabetes mellitus and cancers." (PMID 26692905, 2015). "Experimental diabetes significantly decreased the ratio of MMP-8 to TIMP-1 and MMP-9 to TIMP-1 compared with that of the NG (P<0.05)." (PMID 25289023, 2014). "In the DG, diabetes decreased the expression levels of MMP-8 and MMP-9 induced by mandibular advancement and increased the expression levels of TIMP-1 compared with that of the NG." (PMID 25289023, 2014). "Oxidative stress is present in diabetes, and elevated levels of reactive oxygen species can lead to elevated MMP2 and MMP9 levels." (PMID 25204377, 2014). "Intravitreal administration of the ERK1/2 inhibitor U0126 prior to induction of diabetes decreased ERK1/2 activation, attenuated diabetes-induced upregulation of MMP-9, iNOS, IL-6, and TNF-α and upregulated TIMP-1 expression." (PMID 23671886, 2013). "We found that diabetes significantly resulted in increased expression of RAGE, TLR4 and MMP9 in damaged arteries which also correlated with intracranial formation of aneurysms." (PMID 23844137, 2013). "Bone marrow EPCs mobilization is delayed and reduced in diabetes, with impaired HIF/p-Akt/p-eNOS/MMP-9 signaling." (PMID 23226370, 2012). "Immunohistochemical procedures for MMP-2, MMP-9, TNF-α, IL-1β, IL-6, RANKL, and RAGE were performed in rats after 1, 3, 6, 9, and 12 months of diabetes induction." (PMID 22611374, 2012). "In diabetes mellitus patients, TGF-β1 and MMP-9 activity alteration occurs in delayed healing." (PMID 37172947, 2024). "In a study of adult patients with type 1 diabetes without vascular complications (n = 47) MMP-9 was higher than in controls without diabetes and higher in patients with retinopathy than patients without retinopathy." (PMID 38932813, 2024). "In addition, spironolactone significantly attenuated the diabetes-induced increase in both urine MMP2 and MMP9 activities, confirming that MR antagonism reduced the activity of both MMPs in vivo." (PMID 36749631, 2023). "In patients with CKD and diabetics, serum levels of MMP-2, MMP-8, and MMP-9 were found to be higher, being correlated with serum phosphate (MMP-2), fibroblast growth factor-23 (FGF-23), and proteinuria (MMP-8 and MMP-9), which are both associated with oxidative stress and cardiovascular health." (PMID 37840653, 2023). "Besides obesity and diabetes, serum concentration and expression levels of MMP2 and MMP9 have also been studied in non-alcoholic fatty liver disease (NAFLD)." (PMID 37445827, 2023). "Previous studies have also found increased MMP-8 (and MMP-9) levels and less favorable healing process in the gingival tissues of patients with chronic periodontitis and diabetes compared with periodontitis patients without diabetes." (PMID 38001886, 2023). "Therefore, this study confirmed that a mixture of Korean red ginseng and probiotics, which are known to be effective in treating diabetes and general wounds, can help heal wounds by controlling the expression of TNF-α, MMP-9, TIMP-1, and NF-κB." (PMID 37374359, 2023). "Therefore, we investigated the effect of Nimbidiol on the expression of MMP-9 and MMP-13 in the diabetic kidney." (PMID 36522378, 2022). "We compared MMP-9 and MMP-14 levels in vitreous between diabetic and non-diabetic groups to analyze novel markers of diabetic retinopathy as diabetes is a risk factor of diabetic retinopathty." (PMID 35729613, 2022). "Serum MMP-9 levels were significantly higher in smokers with diabetic CHD individuals compared to CHD without diabetes and the control group (p<0.0001)." (PMID 36110446, 2022).
diabetes (continued). "The results were supported by another study in which no changes in the circulating levels of MMP-9 were observed between TB patients with or without diabetes." (PMID 36776550, 2022). "The effect of baseline plasma free MMP-9 levels on the decline in MMSE scores among women remained significant (β=−2.12; 95% CI, −4.02 to −0.25; p=0.028) after further adjustment for hypertension, diabetes, and smoking." (PMID 36324151, 2022). "Therefore, hMSC-EC secretome, particularly a cocktail of angiopoietin-1 and 2, FGF-7, MMP-9, and VEGF-C, are potential new therapeutic targets for improving wound-healing in diabetes." (PMID 35055129, 2022). "However, in the diabetic OA and the MMP8 and MMP9 overexpressing group (Diabetic OA-OE), matrix staining was weakened and unevenly distributed." (PMID 33468174, 2021). "The present study evaluates the levels of MIF and MMP-9 in non-diabetics in the families with family members who have type 2 diabetes mellitus." (PMID 34567195, 2021). "The imbalance of MMP2/TIMP2 and MMP9/TIMP1 contributes to the non-injured skin disorder of collagen deposition in diabetes, suggesting a possibility for early treatment of diabetes skin complications." (PMID 34777244, 2021). "This difference in VEGF levels could be explained by the fact that diabetes mellitus (DM) was also induced in these rats, a metabolic pathology in which VEGF levels diminish and MMP-9 levels increase, altering the cicatrisation process." (PMID 34667500, 2021). "The gelatinases, MMP2 and MMP9, mediate fibrosis in CKD, such as in diabetes mellitus." (PMID 34819020, 2021). "For example, in the amelioration of diabetes, miR-129-3p decreases the apoptosis and recruitment of neutrophils by regulating the translation of Casp6 and Ccr2, whereas miR-129-5p inhibits ECM degradation by inhibiting the expression of Sp1-mediated MMP9." (PMID 34777000, 2021). "The most powerful risk factors for MACE, during the analysis of all included patients (STEMI and NSTEMI), identified with univariable analysis (diabetes, depressed LVEF, increased levels of hs-CRP, I-CAM and MMP-9), were included in a multivariable model for predicting MACE." (PMID 34362217, 2021). "Indeed MMP9 can be the link: while in diabetes MMP9 is overexpressed due to SIRT1-deficit, there are also results confirming activation of MMP9 in the diabetic retina by extracellular signal-regulated kinase (ERK) MAP kinase pathway." (PMID 32204537, 2020). "In diabetes—due to over-transactivation by dysregulated transcription factors (NF-kappaB, PARP1 etc.)—excess levels of MMP9 transported into the mitochondria may lead to mitochondrial damage." (PMID 32204537, 2020). "Type IV collagenases, MMP-2 (72kDa), and gelatinase-B, MMP-9 (92kDa) are most likely to contribute to the microvascular complications of diabetes mellitus, especially in diabetic retinopathy due to capillary cell apoptosis mechanism as previously reported on animal models." (PMID 30818888, 2019). "We found MMP-9 expression was positively correlated with TETILA expression in human skin tissue with diabetes (n = 10) and non-diabetes (n = 10) (P = 0.040)." (PMID 31653825, 2019). "In addition, we performed multiple logistic regressions to evaluate the predictive value of serum MMP9 and TLR4 in AAD with the adjustment for age, gender, smoking, drinking, hypertension, diabetes and hyperlipidemia." (PMID 30497388, 2018). "In our study, diabetes treated with oral antidiabetic medication did not influence the plasma levels of MMP-9 and TIMP-1 at any time point." (PMID 30157791, 2018). "In the subgroup comparisons stratified by age, gender, hypertension, diabetes and hyperlipidemia, we found that both AAA and TAA patients had higher MMP9 levels in the subjects aged <65 years, either male or female, and hypertensive status compared with controls." (PMID 30373522, 2018).
diabetes (continued). "Compared to control group, both AAA and TAA patients had higher serum MMP9 levels in the overall comparison and subgroup analysis based on subjects aged<65 years, either male or female, hypertension, non-diabetes and non-hyperlipidemia (all P<0.05)." (PMID 30373522, 2018). "Since we previously found that the expression of MMP‐1 and MMP‐9 are increased subsequent to MAC‐SMC cross talk, we questioned now whether HG (ie diabetes) has an effect on this interaction." (PMID 29992758, 2018). "Another group also reported that mice with STZ-induced diabetes had elevated expression of osteoclast-specific genes (matrix metallopeptidase-9, carbonic anhydrase II, RANKL) in tibiae than non-diabetic mice." (PMID 30413166, 2018). "There is solid evidence that the prognosis of AMI is associated with various factors, including dyslipidemia, smoking status, hypertension, diabetes mellitus, age, male gender, and plasma levels of B-type natriuretic peptide (BNP) and matrix metalloproteinase-9 (MMP-9)." (PMID 29285294, 2017). "MMP-9 plays a key role in the remodeling of ECM due to its ability to degrade Col IV, which is a major component of the glomerular basement membrane increased at both sites in experimental and human diabetes." (PMID 28662169, 2017). "Additionally the effect of diabetes on NGAL and MMP-9 levels in wound and in circulating neutrophils has received little attention." (PMID 28182694, 2017). "The associations between MMP-1, MMP-9, MMP-10, and TIMP-1 with cfPWV did not materially change after adjustment for age instead of age and diabetes duration." (PMID 29070037, 2017). "On the other hand, subjects without diabetes had similar MMP-9 level comparing those with positive and negative P. intermedia scores." (PMID 26989414, 2016). "Diabetes can also induce expression of TNF-α, MMP-2, and MMP-9 in the retina which may enhance apoptosis in the tissue and contribute to the pathogenesis of diabetic retinopathy." (PMID 25821481, 2015). "Factors with non-significant associations with MMP-9 were age, total cholesterol, non-HDL cholesterol levels, angina pectoris at baseline, diabetes at baseline, use of statins and antihypertensive drugs." (PMID 26389803, 2015). "Diabetes downregulated MMP-9 expression, the ratio of MMP-9 to TIMP-1 and the total layer thickness of the cartilage, which implies that diabetes may alter the condylar response to mandibular forward positioning." (PMID 25289023, 2014). "Inflammatory mediators including MMP9, RAGE and TLR4 in diabetes might contribute the increased initiation and formation of aneurysm and arteriosclerosis." (PMID 23844137, 2013). "Rodent models of diabetes revealed the decreased expression of MMP-2 and MMP-9 in renal tissues." (PMID 23819050, 2013). "In addition, other authors have evaluated the influence of diabetes in MMPs expression, demonstrating higher levels of MMP-8 and MMP-9 in periodontal tissue of diabetic patients with periodontitis." (PMID 22611374, 2012). "Alloxan-induced diabetes MMP-9 -/- mice did not have induced apoptosis and did not have a decrease in endothelial cell density when compared to wild type alloxan-induced diabetes." (PMID 15985157, 2005). "The absence of correlation between serum MMP-9 and HbA1c (p>0.05) or diabetes duration presents a paradigm-shifting insight, although these results could be skewed by the small sample size." (PMID 41189831, 2025). "Furthermore, neutrophil-released NETs, through the IL-8 and MMP-9 they carry, jointly activate the profibrotic phenotype of FBs and directly exacerbate extracellular matrix (ECM) degradation, impeding skin wound healing in diabetes." (PMID 41262541, 2025). "We present a combination of in vitro experiments, in vivo animal, and human data in patients with type 2 diabetes mellitus (T2DM) and indicate that MMP9 may be potentially useful for the early detection of carotid artery plaque and coronary artery plaques in patients with diabetes." (PMID 38660518, 2024).
diabetes (continued). "Moreover, diabetes activated the expression of MMP-9 regulated by H-Ras and increased MMP-9 activity in the retina of patients with diabetic retinopathy, requiring antioxidant strategies based on plant extracts to inhibit ROS production or to stimulate the endogenous antioxidant system." (PMID 39770580, 2024). "However, MMP9 levels and HbA1c concentrations did not correlate with each other, therefore it is unlikely that diabetes severity influences MMP9 concentrations." (PMID 36609276, 2023). "Moreover, higher concentrations of MMP9 were observed in metabolic syndrome patients with diabetes mellitus, compared to metabolic syndrome patients without diabetes." (PMID 37445827, 2023). "Further, diabetes and hyperglycemic conditions lead to a decrease in levels of MCP-1, increased gene expression of mmp-1, and decreased gene expression of mmp-9, which together may lead to a disruption in the process of granuloma formation and in the activation of latent TB infection." (PMID 36776550, 2022). "When compared to CHD subjects without diabetes, inflammatory markers (hsCRP, MMP-9) gradually increased in smokers with diabetes (“p-value” 0.0001), indicating that smokers with CHD who have a complication of diabetes significantly increase the systemic inflammation." (PMID 36110446, 2022). "Obtained results showed that either genetic or pharmacological strategies may contribute to the reduction of albuminuria, glomerular hypertrophy, mesangial expansion, renal inflammation, and fibrosis induced by diabetes via regulation of MMP2, MMP9, and ADAM17 activities." (PMID 33634991, 2021). "Numerous studies in the literature have shown that MMPs (such as MMP-2, MMP-7, MMP-8, MMP-9, MMP-14) register altered values in patients with DM (types 1 and 2) and this seems to contribute to several complications of diabetes." (PMID 34829612, 2021). "Also, at Day-7 post-wounding, MMP-9 was expressed at basal levels in skin tissues of the non-diabetic group, but was highly expressed in those with diabetes, which was consistent with our previous studies." (PMID 33952251, 2021). "Some comorbid conditions other than diabetes mellitus such as renal scars, nephrotic syndrome, focal segmental glomerulosclerosis, pancreatic cancer and chronic kidney failure may also affect urine MMP2 and MMP9, TIMP1 and TIMP2 and TGF-β1 concentrations." (PMID 30396876, 2019). "However, in the non-diabetes and non-hyperlipidemia status, MMP9 levels were obviously higher from control to AAA to TAA group (all P < 0.05)." (PMID 30373522, 2018). "In addition, MMP9 levels showed to increase from control to AAA to TAA group in the non-diabetes and non-hyperlipidemia status." (PMID 30373522, 2018). "Importantly, the role of MMP-9 is not restricted to cardiovascular disorders; it is also involved in the progression of microalbuminuria in non-insulin-dependent diabetes mellitus." (PMID 29693002, 2018). "In addition, renal transplant recipients with diabetes had stiffer arteries compared to recipients without diabetes and controls, and this was significantly associated with higher MMP-2 and MMP-9 activity in the arterial wall." (PMID 29070037, 2017). "Similarly, reinstitution of good control after 3 months of poor control in rats did not reverse diabetes-induced increase in retinal Dnmt1 and Tet2, and alter the methylation status of mtDNA and MMP-9." (PMID 27787562, 2016). "Thus, in addition to angiogenic factors, MMP-9 and MMP-13 may play a role in wound healing in patients with diabetes." (PMID 25884474, 2015). "In addition we found no constitutive or diabetes-associated expression of MMP-9, but confirmed MMP-9 upregulation following nerve injury." (PMID 25158309, 2014). "The MMP-9 gelatinase levels in the retinas of diabetic rats were increased by about 40%, 55%, 85%, and 50% at 1, 4, 8, and 12 weeks, respectively, after the onset of diabetes compared to nondiabetic rats." (PMID 23671886, 2013).